PSMA7 (proteasome 20S subunit alpha 7)
Description:
Component of the 20S core proteasome complex involved in the proteolytic degradation of most intracellular proteins. This complex plays numerous essential roles within the cell by associating with different regulatory particles. Associated with two 19S regulatory particles, forms the 26S proteasome and thus participates in the ATP-dependent degradation of ubiquitinated proteins. The 26S proteasome plays a key role in the maintenance of protein homeostasis by removing misfolded or damaged proteins that could impair cellular functions, and by removing proteins whose functions are no longer required. Associated with the PA200 or PA28, the 20S proteasome mediates ubiquitin-independent protein degradation. This type of proteolysis is required in several pathways including spermatogenesis (20S-PA200 complex) or generation of a subset of MHC class I-presented antigenic peptides (20S-PA28 complex). Inhibits the transactivation function of HIF-1A under both normoxic and hypoxia-mimicking conditions. The interaction with EMAP2 increases the proteasome-mediated HIF-1A degradation under the hypoxic conditions. Plays a role in hepatitis C virus internal ribosome entry site-mediated translation. Mediates nuclear translocation of the androgen receptor (AR) and thereby enhances androgen-mediated transactivation. Promotes MAVS degradation and thereby negatively regulates MAVS-mediated innate immune response.
Synonyms: HSPC; XAPC7; C6; RC6-1; HEL-S-276
Tractability: Small molecule: an approved drug acts on it; a structure with a bound ligand is known; a high-quality ligand is known; it belongs to a druggable protein family. PROTAC: ubiquitination databases record sites on it; its protein half-life has been measured; a small molecule that binds it is known.
Gene: Protein-coding gene on chromosome 20 (62,136,728 to 62,143,452, reverse strand). Ensembl gene ENSG00000101182.
Subcellular location: Cytoplasm; Nucleus
Subcellular location (Human Protein Atlas): Principal piece; Vesicles
Pathways (Reactome):
Immune System: AMPK-induced ERAD and lysosome mediated degradation of PD-L1(CD274); Activation of NF-kappaB in B cells; Antigen processing: Ub, ATP-independent proteasomal degradation; Antigen processing: Ubiquitination & Proteasome degradation; CLEC7A (Dectin-1) signaling; Cross-presentation of soluble exogenous antigens (endosomes); Dectin-1 mediated noncanonical NF-kB signaling; Downstream TCR signaling; ER-Phagosome pathway; FCERI mediated NF-kB activation; GSK3B-mediated proteasomal degradation of PD-L1(CD274); Interleukin-1 signaling; NIK-->noncanonical NF-kB signaling; SPOP-mediated proteasomal degradation of PD-L1(CD274); TNFR2 non-canonical NF-kB pathway
Cell Cycle: APC/C:Cdc20 mediated degradation of Securin; APC/C:Cdh1 mediated degradation of Cdc20 and other APC/C:Cdh1 targeted proteins in late mitosis/early G1; Autodegradation of Cdh1 by Cdh1:APC/C; Autodegradation of the E3 ubiquitin ligase COP1; Cdc20:Phospho-APC/C mediated degradation of Cyclin A; FBXL7 down-regulates AURKA during mitotic entry and in early mitosis; G2/M Checkpoints; SCF(Skp2)-mediated degradation of p27/p21; SCF-beta-TrCP mediated degradation of Emi1; Separation of Sister Chromatids; The role of GTSE1 in G2/M progression after G2 checkpoint; Ubiquitin-Mediated Degradation of Phosphorylated Cdc25A; Ubiquitin-dependent degradation of Cyclin D
Signal Transduction: Asymmetric localization of PCP proteins; Degradation of AXIN; Degradation of DVL; Degradation of GLI1 by the proteasome; Degradation of GLI2 by the proteasome; Degradation of beta-catenin by the destruction complex; GLI3 is processed to GLI3R by the proteasome; Hedgehog 'on' state; Hedgehog ligand biogenesis; MAPK6/MAPK4 signaling; Negative regulation of NOTCH4 signaling; Regulation of PTEN stability and activity
and 28 more pathways
Gene Ontology:
Molecular function: identical protein binding; protein binding; structural constituent of proteasome
Biological process: proteasomal protein catabolic process; proteasome-mediated ubiquitin-dependent protein catabolic process; regulation of proteasomal protein catabolic process; response to oxidative stress; apoptotic process; CD8-positive, alpha-beta T cell differentiation; CD8-positive, alpha-beta T cell homeostasis; cellular response to type I interferon; DNA damage response; DNA repair; flagellated sperm motility; immune system process; negative regulation of regulatory T cell differentiation; positive regulation of interleukin-2 production; positive regulation of tumor necrosis factor production; positive regulation of type II interferon production; proteasomal ubiquitin-independent protein catabolic process; regulation of G1/S transition of mitotic cell cycle; response to type II interferon; T-helper 1 cell differentiation; T-helper 17 cell differentiation; thymic T cell selection; protein catabolic process; ubiquitin-dependent protein catabolic process
Cellular component: cytoplasm; extracellular exosome; nucleus; proteasome complex; proteasome core complex; proteasome core complex, alpha-subunit complex; cytosol; nucleoplasm; proteasome storage granule; synaptic vesicle
Genetic constraint (gnomAD): Loss-of-function variants: 5 observed, 28.63 expected, observed/expected ratio (o/e) 0.17, 90% interval 0.09 to 0.37. The synonymous counts are far from expectation, so gnomAD's model fits this gene poorly and the ratio says little. Missense variants: 217 observed, 308.53 expected, observed/expected ratio (o/e) 0.7, 90% interval 0.63 to 0.79. Synonymous variants: 155 observed, 122.75 expected, observed/expected ratio (o/e) 1.26, 90% interval 1.11 to 1.44.
Homologues: Orthologues: chimpanzee PSMA7 (99% identical), macaque PSMA7 (99% identical), mouse Psma7 (99% identical), rat Psma7 (99% identical), guinea pig PSMA7 (97% identical), tropical clawed frog psma7 (96% identical), pig PSMA7 (87% identical), Caenorhabditis elegans pbs-1 (15% identical), Drosophila melanogaster Prosbeta1 (13% identical). Paralogues in human: PSMA8 (84% identical), PSMA4 (38% identical), PSMA2 (35% identical), PSMA1 (34% identical), PSMA5 (34% identical), PSMA3 (33% identical), PSMA6 (32% identical), PSMB7 (19% identical), PSMB10 (18% identical), PSMB4 (17% identical), PSMB9 (17% identical), PSMB5 (16% identical), and 6 more.
Diseases named in the same sentence as PSMA7 in open-access papers:
PSMA7 is named in the same sentence as 82 diseases in open-access papers, as found by Europe PMC text mining. Sharing a sentence is not in itself a finding about the gene and the disease. The quoted sentences say what the papers report.
colorectal cancer (7 papers, 2009 to 2021). A primary or metastatic malignant neoplasm that affects the colon or rectum. "One clue provided by a previous study showed that overexpression of PSMA7 in protein level was significantly associated with liver metastasis and worse prognosis in colorectal cancer." (PMID 27966459, 2017). "In colorectal cancer, it was previously reported that the mRNA and protein expression levels of PSMA7 were much higher than in normal tissue, and a high protein expression of PSMA7 was significantly associated with worse OS for colorectal cancer patients." (PMID 27966459, 2017). "In addition, the expression of PSMA7 has been shown to be overexpressed in colorectal cancer and was significantly associated with prognosis in cancer patients." (PMID 27966459, 2017). "Studies reported that PSMA7 expression was elevated in testicular, liver, breast, prostate, cervical, gastric, and colorectal cancers, while UBA52 is overexpressed in the colon, and renal cancers." (PMID 34777463, 2021). "In line with this study, eight comparisons from five datasets including Ki, Skrzypczak, TCGA, Skrzypczak 2 and Hong revealed that the mRNA level of PSMA7 was increased in different types of colorectal cancer compared with normal tissues." (PMID 27966459, 2017). "Depletion of PSMA7 in colorectal cancer cells had an inhibition effect on cell invasion and migration." (PMID 27966459, 2017). "In another study that used small interfering RNA to knockdown PSMA7, increased expression of 97 genes was detected in human colorectal cancer cells (HT-29) exhibiting increased apoptosis." (PMID 28523434, 2017). "In the TCGA database, PSMA1-5 and PSMA7 were overexpressed in colorectal cancer tissues examined by mRNA HiSeq expression data." (PMID 27966459, 2017). "Macropain (PSMA7) is increased in brain, breast, and stomach cancer, and plays an important role in colorectal cancer progression providing a unique target for drug development." (PMID 19347046, 2009). "Furthermore, colorectal cancer has shown overexpressed levels of PSMA7 that are meaningfully related to the cancer patient's prognosis." (PMID 33906413, 2021). "Interestingly, it has been shown that PSMA7 depletion in colorectal cancer cells leads to decreased cell invasion and migration." (PMID 33906413, 2021). "Depletion of PSMA7 using shRNA was also found to inhibit colorectal cancer cell growth in vitro." (PMID 32850906, 2020). "PSMA7 is also considered a novel biomarker of colorectal cancer." (PMID 28523434, 2017). "PSMA7 is highly expressed in colorectal cancer cells compared with normal colonic tissues." (PMID 28523434, 2017). "Consequently, inhibition of PSMA7 could be a beneficial therapeutic strategy for colorectal cancer patients." (PMID 34249670, 2021). "PSMA7 may be a target site of drugs based on interference with colorectal cancer treatment." (PMID 28523434, 2017). "Meanwhile a large number of literatures have reported that PSMA7 has increased in IBD intestinal fluid, tissue, or in colorectal cancer, or some other digestive diseases." (PMID 28523434, 2017). "NOD1 is regulated by PSMA7 in a proteasome-dependent manner, and overexpression of PSMA7 inhibits NOD1-mediated colorectal cancer cell apoptosis." (PMID 27966459, 2017). "In colorectal cancer, PSMA1-5 and PSMA7 were demonstrated to be overexpressed in tumor tissues." (PMID 27966459, 2017). "Although PMSA7 knockdown in colorectal cancer cell line RKO showed no impact on proliferation or cell cycle, depletion of PSMA7 was demonstrated to significantly suppress tumor formation in vitro and in vivo, as well as inhibit RKO cell invasion and migration." (PMID 27966459, 2017).
breast carcinoma (6 papers, 2017 to 2025). "High-expressed PSMA family genes (e.g., PSMA2, PSMA3, PSMA4, PSMA6, and PSMA7) in breast cancer tissues are reported to be linked to a poor OS of the cancer, but higher levels of PSMA5 and PSMA8 are indicative of better clinical outcomes." (PMID 41141246, 2025). "As expected, breast cancer patients with elevated PSMA7 expression exhibited poor OS, relapse-free survival (RFS), and DFS." (PMID 38321088, 2024). "PSMA2, PSMA3, PSMA4, PSMA6, and PSMA7 showed high expression levels, which were correlated with poor survival of breast cancer patients." (PMID 36424389, 2022). "The mRNA level of PSMA7 was higher in breast cancer than in normal samples in Richardson's datasets 2, but was lower in Finak's study." (PMID 27966459, 2017). "Furthermore, PSMA2, PSMA3, PSMA4, PSMA6, and PSMA7 showed high expression levels, which were correlated with poor survival of breast cancer patients." (PMID 34943457, 2021).
gastric cancer (6 papers, 2009 to 2024). A primary or metastatic malignant neoplasm involving the stomach. "The overexpression of PSMA7 was associated with poor prognosis in patients with gastric cancer." (PMID 36232418, 2022). "PSMA7 and GID8 are two genes encoded within 20q13.33 that were described as possible gene targets in gastric cancer." (PMID 36232418, 2022). "In gastric cancer, elevated PSMA7 expression merely exhibited a significant link with inferior FP." (PMID 38321088, 2024). "Overexpression of PSMA7 both at the mRNA and protein levels has been reported in gastric cancer." (PMID 34249670, 2021). "PSMA7, through the mitogen-activated protein kinase (MAPK) pathway, promotes the proliferation and metastasis of gastric cancer." (PMID 34943457, 2021). "In Oncomine database, there were five datasets that compared the expression differences between gastric cancer and normal tissues for PSMA1-6, and four datasets for PSMA7." (PMID 27966459, 2017).
bladder cancer (3 papers, 2019 to 2022). "This study also reveals that PSMA7 is a potential therapeutic target for bladder cancer, with overexpression in MIBC and poor prognosis." (PMID 36741702, 2022). "Weighted gene co-expression network analysis (WGCNA), protein–protein interaction (PPI) network mutual analysis, and the Kaplan–Meier survival prognosis analysis were used to identify six key genes associated with the prognosis of bladder cancer: VEGFA, ANXA1, HSP90B1, PSMA7, PRDX6, and PPP1CB." (PMID 36741702, 2022). "According to BC values and the Kaplan–Meier survival curve, six genes related to the occurrence and development of bladder cancer were screened out: VEGFA, ANXA1, HSP90B1, PSMA7, PRDX6, and PPP1CB." (PMID 36741702, 2022). "The Kaplan–Meier survival prognosis analysis was performed on the top 100 genes, and 6 genes related to the survival prognosis of bladder cancer were finally screened out: VEGFA, ANXA1, HSP90B1, PSMA7, PRDX6, and PPP1CB." (PMID 36741702, 2022).
colon carcinoma (3 papers, 2017 to 2022). "Previous studies reported that increased PSMA7 expression was associated with the liver metastasis of colon cancer or depressive disorders." (PMID 33050496, 2020). "Increased expression of PSMA7 is associated with liver metastasis of colon cancer and reduced survival rate of patients, suggesting the potential for proteasome inhibitors in clinical therapeutic applications." (PMID 28523434, 2017). "The mechanism of PSMA7 in colon cancer may also be explained by tumor angiogenesis, which is an important biological process in IBD pathology." (PMID 28523434, 2017). "Abnormal PSMA7 activation can significantly regulate colon cancer metastasis." (PMID 28523434, 2017). "Furthermore, it has been shown that PSMA7 plays a role in the progression of colon cancer and may be a unique target for drug treatment." (PMID 28523434, 2017).
lung cancer (3 papers, 2017 to 2024). A malignant neoplasm involving the lung. "In lung cancer, PSMA1-2, PSMA4 and PSMA5 were correlated with better prognosis, whereas PSMA6 and PSMA7 predicted worse survival outcomes." (PMID 27966459, 2017). "The meta-analysis of these survival data further confirmed that PSMA7 overexpression was an adverse factor for breast, gastric, and liver cancers but not ovarian or lung cancers." (PMID 38321088, 2024). "Similarly, overexpressed PSMA7 showed a connection with adverse OS but not PFS or post-progression survival (PPS) for ovarian cancer, whereas poor OS and PPS but good first progression (FP) for lung carcinoma." (PMID 38321088, 2024).
COVID-19 (2 papers, 2023 to 2024). A disease caused by infection with severe acute respiratory syndrome coronavirus 2. "Fifteen proteasomal proteins showed an increase in serum levels of COVID-19 patients, most notably PSMA7, PSME1, PSMB3, PSMA4 and PSMA5, whereas PSMD2 was the only one with decreased levels." (PMID 37739942, 2023). "Multiple proteasome subunits (e.g., PSMA1, PSMA5, PSMA6, PSMA7, and PSMB1) were upregulated in COVID-19 patients, especially during the acute phase of disease, potentially contributing to the dysregulation of proteasome activity." (PMID 38965561, 2024).
diabetes (2 papers, 2017 to 2020). "In the group enriched with diabetic patients (6 out of 9 patients), seven proteasome genes (PSME4, PSMA7, PSMB4, PSMB6, PSMC4, PSMD7 and PSMD8) and three genes previously associated with common diabetes (SNX17, PARK7/DJ-1 and ATP5B) were highly expressed." (PMID 32302349, 2020).
germ cell tumor (2 papers, 2024 to 2025). A benign or malignant, gonadal or extragonadal neoplasm that originates from germ cells. "Together, these findings suggest that DPPA4 and PSMA7 promote tumor progression, whereas PAGE5 and SAT1 suppress progression in germ cell tumors." (PMID 41203637, 2025).
lung squamous cell carcinoma (2 papers, 2017 to 2024). "As for PSMA7, the mRNA expression level was dramatically elevated in squamous cell lung carcinoma." (PMID 27966459, 2017). "In addition, the amplified CNA of PSMA7 predominated in each type of tumor with a frequency of up to 80%, while the copy number deletion was most frequently observed in less than 15% of patients with lung squamous cell carcinoma (LUSC)." (PMID 38321088, 2024).
amyotrophic lateral sclerosis (1 paper, 2022). Amyotrophic lateral sclerosis (ALS) is a neurodegenerative disease characterized by progressive muscular paralysis reflecting degeneration of motor neurons in the primary motor cortex, corticospinal tracts, brainstem and spinal cord. "PSMA7 has been implicated in cancer and amyotrophic lateral sclerosis (ALS), yet its mechanism of action remains to be elucidated in those models." (PMID 36357363, 2022).
cervical cancer (1 paper, 2022). A primary or metastatic malignant neoplasm involving the cervix. "Recent studies have shown that PSMA7 silencing can promote apoptosis by inhibiting UPP signaling pathway, as well as inhibiting cervical cancer cell proliferation and VEGF expression." (PMID 36741702, 2022).
colon adenocarcinoma (1 paper, 2024). "The uterine carcinosarcoma (UCS) cases carried the utmost amplification incidence of PSMA7 (~ 8.8%), followed by colon adenocarcinoma (COAD) (~ 6.7%) and OV (~ 6.2%)." (PMID 38321088, 2024).
embryonal carcinoma (1 paper, 2025). A non-seminomatous malignant germ cell tumor characterized by the presence of large germ cells with abundant cytoplasm resembling epithelial cells, geographic necrosis, high mitotic activity, and pseudoglandular and pseudopapillary structures formation. "Genes such as DPPA4 and PSMA7 were highly expressed in tumor cells characterized by elevated stemness and enhanced metastatic ability, including embryonal carcinoma and metastatic seminoma, and were linked to disease progression in TCGA analyses." (PMID 41203637, 2025).
endometrial cancer (1 paper, 2024). Primary or metastatic malignant neoplasm involving the endometrium (mucous membrane that lines the endometrial cavity). "By contrast, a 3-marker panel of plasma proteins combining APOD, PSMA7 and HPT predicted endometrial cancer with an AUC of 0.87 (0.81–0.93), sensitivity of 75%, and specificity of 84%." (PMID 38513301, 2024). "By contrast, a 3-marker panel of plasma proteins (APOD, PSMA7 and HPT) predicted endometrial cancer with an AUC of 0.87 (0.81–0.93), sensitivity of 75% (64%–86%), and specificity of 84% (75%–93%)." (PMID 38513301, 2024). "A 3-marker panel combining APOD, PSMA7 and HPT, predicted endometrial cancer with an AUC of 0.87 (0.81–0.93), sensitivity of 75% (64%–86%), specificity of 84% (75%–93%), and had the least AIC value." (PMID 38513301, 2024).
female infertility (1 paper, 2026). Diminished or absent ability of a female to achieve conception. "Consequently, maternal Psma7 deletion resulted in female infertility, manifested by impaired oocyte maturation and developmental arrest at one- to two-cell stage." (PMID 42168604, 2026).
gastric intestinal type adenocarcinoma (1 paper, 2017). An adenocarcinoma of the stomach arising on a background of intestinal metaplasia. "However, compared with 31 gastric mucosa samples, the mRNA expression level of PSMA7 was significantly upregulated in gastric intestinal type adenocarcinoma (cases = 26, fold change = 2.516, p < 0.001) and gastric mixed adenocarcinoma (cases = 4, fold change = 2.555, p < 0.001) in DErrico's dataset." (PMID 27966459, 2017).
Hepatitis (1 paper, 2005). Inflammation of the liver. "In consideration of the close correlation of hepatitis with HCC, upregulation of PSMA7 in HCC may play an important role in aetiopathogenesis of HCC." (PMID 15756260, 2005).